HNF1B (HNF1 homeobox B)
Diseases named in the same sentence as HNF1B in open-access papers (continued):
Sharing a sentence is not in itself a finding about the gene and the disease.
esophageal carcinoma (1 paper, 2020). A primary or metastatic malignant neoplasm involving the esophagus. "Moreover, there was a strong positive correlation between HNF1B expression and CD4+ T cell levels in esophageal carcinoma (ESCA, r = 0.317, p =1.45e-5), Uterine Carcinosarcoma (UCS, r = 0.338, p =1.32e-02), liver hepatocellular carcinoma (LIHC, r= 0.451, p = 1.02e-18)." (PMID 33173410, 2020).
Fanconi syndrome (1 paper, 2013). "However, the characteristics of this model (i.e. induction of complete proximal tubule dysfunction leading to a renal Fanconi syndrome phenotype) precluded any analogy concerning the role of the Hnf-1β transcription factor during renal repair following ischemic insult." (PMID 23704921, 2013).
gastric cancer (1 paper, 2024). A primary or metastatic malignant neoplasm involving the stomach. "Circ50547 acted as a sponge for miR-217 to regulate the expression of HNF1B, affecting the cancer stem cell-like properties, proliferation, migration, and invasion of gastric cancer cells, ultimately enhancing the drug resistance of gastric cancer cells." (PMID 39314750, 2024).
gestational diabetes (1 paper, 2021). Carbohydrate intolerance first diagnosed during pregnancy. "An exception was the His336Asp mutation in HNF1B in a patient (P27) with gestational diabetes." (PMID 33477506, 2021).
hyperbilirubinaemia (1 paper, 2020). "Hepatic dysfunction affects 65% of patients with hnf1b deletions, characterised by elevated serum transaminases, alkaline phosphatase and sometimes mild hyperbilirubinaemia." (PMID 32864159, 2020).
hyperplasia (1 paper, 2023). An abnormal increase in the number of cells in an organ or a tissue with consequent enlargement. "Patients with HNF1B mutations have a higher risk of developing hepatic lesions, such as liver adenomas and focal nodular hyperplasia, which can lead to hepatic dysfunction and potentially even liver failure." (PMID 37511676, 2023).
incontinentia pigmenti (1 paper, 2021). Incontinentia pigmenti (IP) is a rare X-linked dominant multi-systemic ectodermal dysplasia usually lethal in males and presenting neonatally in females with a bullous rash along Blashko's lines (BL) followed by verrucous plaques evolving over time to hyperpigmented swirling patterns. "In this case report, we described an unusual prenatal diagnosis that revealed a mutation in the HNF1b gene in the fetus of a woman affected by incontinentia pigmenti." (PMID 33259036, 2021).
Jaundice (1 paper, 2022). Yellow pigmentation of the skin due to bilirubin, which in turn is the result of increased bilirubin concentration in the bloodstream. "HNF1B encodes a transcription factor called hepatic nuclear factor-1 β (HNF1B), which is involved in bile duct organogenesis, and its deletion has been shown to induce jaundice, and anomalies of gall bladder." (PMID 35741793, 2022).
leukopenia (1 paper, 2022). "Another study suggested that the lnc-HNF1B-3:1 rs2542670 polymorphism was associated with a higher risk of thrombocytopenia, leukopenia following medication in PTB patients." (PMID 36569862, 2022).
metanephric adenoma (1 paper, 2020). A benign, well-circumscribed renal cortical neoplasm affecting females more often than males. "Given that HNF1B is consistently reported as being overexpressed in adult tumours of embryonal origins (papRCC, but also mucinous tubular spindle cell carcinoma and metanephric adenoma), this overexpression may be a driver of papRCC development." (PMID 33051485, 2020).
metastasis (1 paper, 2022). The spread or migration of cancer cells from one part of the body (where they first appeared) to another. "Patients with higher levels of HNF1B cell cycle signature score are strongly associated with PCa severity, including Gleason score, lymph node metastasis, tumor stage, and biochemical recurrence." (PMID 36443337, 2022).
metastatic prostate carcinoma (1 paper, 2020). A carcinoma that arises from the prostate gland and has spread to other anatomic sites. "Both mRNA and protein levels of EZH2 were high accompanied with low HNF1B-expressing in the metastatic prostate cancer cell lines PC-3 and DU145." (PMID 31636385, 2020). "Significant reverse correlation between HNF1B and EZH2 protein levels was also readily identified by IHC analyses in 17 cases of in-house collection of metastatic prostate cancer samples (r = −0.672; P = 0.031)." (PMID 31636385, 2020).
ovarian clear cell adenocarcinoma (1 paper, 2025). A malignant glandular epithelial neoplasm characterized by the presence of clear and hobnail cells. "HNF-1β, expressed in CCAU with a much higher positive rate compared with urothelial carcinoma, is often overexpressed in ovarian clear cell adenocarcinoma." (PMID 40012547, 2025).
ovarian endometriosis (1 paper, 2013). A non-neoplastic disorder characterized by the growth of endometrial tissue in the ovaries. "HNF1B itself has also been reported to be highly expressed in secretory and gestational endometrium, and in ovarian endometriosis (atypical or reactive type) associated with CCC." (PMID 24040285, 2013).
pancreatic exocrine insufficiency (1 paper, 2018). "Pancreatic hypoplasia in HNF1B-associated disease has been associated with subclinical pancreatic exocrine insufficiency." (PMID 30094008, 2018).
papillary thyroid cancer (1 paper, 2013). "Recently, NNMT promoter has been cloned and studied in papillary thyroid cancer cell lines, in which it was shown to be activated by hepatocyte nuclear factor beta (HNF-1β)." (PMID 23990942, 2013). "Moreover, in BHP 18–21 papillary thyroid cancer cells, the histone deacetylase inhibitor depsipeptide reduced NNMT expression through HNF-1β downregulation." (PMID 23990942, 2013).
primary hyperparathyroidism (1 paper, 2020). "Primary hyperparathyroidism has been identified because HNF1B inhibits the transcription of parathormone (pth)." (PMID 32864159, 2020).
prune belly syndrome (1 paper, 2019). "On the other hand, while heterozygous mutations of HNF1B are well-recognized to cause diverse kidney malformation, these patients do not have prune belly syndrome." (PMID 31032239, 2019). "Finally, heterozygous whole gene deletions of HNF1B have been reported in rare patients with prune belly syndrome." (PMID 31032239, 2019). "Moreover, another study found that, while a patient with prune belly syndrome carried a missense variant of HNF1B, this did not affect the transactivation functional of the encoded protein." (PMID 31032239, 2019).
pulmonary embolism (1 paper, 2013). The obstruction of the pulmonary artery or one of its branches by an embolus, sometimes associated with infarction of the lung. "Overall, 55% of cases stained positively for HNF1B by IHC, and 37% of patients experienced one or more clinically-significant venous thromboembolic event, i.e. deep venous thrombosis (DVT), pulmonary embolism (PE), or stroke." (PMID 24040285, 2013).
serous ovarian tumors (1 paper, 2015). "Instead, this SNP was determined to be a methylation eQTL (mQTL), associated with HNF1B promoter methylation in serous ovarian tumors." (PMID 25378557, 2015). "HNF1B expression has also been reported to be lower in primary serous ovarian tumors than in normal ovarian tissue." (PMID 25378557, 2015).
Shock (1 paper, 2013). The state in which profound and widespread reduction of effective tissue perfusion leads first to reversible, and then if prolonged, to irreversible cellular injury. "In this mouse model of hemorrhagic shock-induced AKI, we now show a significant ∼50% decrease in the expression of Hnf1b within the first 10 hours post-shock followed by a transient over-expression at 24 hours." (PMID 23704921, 2013).
squamous cell carcinoma (1 paper, 2015). A carcinoma arising from squamous epithelial cells. "HNF-1β as an adenocarcinoma marker and p63/p40 and D2-40 as a squamous cell carcinoma markers are highly specific with variable sensitivity." (PMID 25884453, 2015). "Squamous cell carcinomas showed expression of HNF-1β in 2/85 cases (2.35%), CEA in 77/85 cases (90.6%), p63 and p40 in 85/85 cases (100%), estrogen receptors in 9/85 cases (10.6%), progesterone receptors in 1/85 cases (1.2%), p16 in 84/85 cases (98.8%), and D2-40 in 45/84 cases (53.6%)." (PMID 25884453, 2015).
Stillbirth (1 paper, 2025). Death of the fetus in utero after at least 22 weeks of gestation. "A study on exome sequencing found that missense mutations of COL2A1, PEIZO1, and HNF1B were associated with stillbirth, and ultra-rare variants in PTPN11, SMC3, and FBN2 were known to cause stillbirth." (PMID 39906474, 2025).
Thromboembolism (1 paper, 2013). The formation of a blood clot inside a blood vessel that subsequently travels through the blood stream from the site where it formed to another location in the body, generally leading to vascular occlusion at the distant site. "Lastly, while our study provides a series of logical connections implicating a casual role of HNF1B in thromboembolism, proof of causality will require definitive studies, e.g. based on the establishment and characterization of a suitable animal model." (PMID 24040285, 2013).
thrombosis (1 paper, 2013). "Here, by integrative computational analysis we link HNF1B transcription factor expression to the production of blood clotting factors by tumor cells, and to an increased risk of venous thrombosis." (PMID 24040285, 2013). "The identification of clotting factor genes among HNF1B targets in ovarian CCC suggests the possibility that HNF1B expression in tumors might increase the risk of venous thrombosis." (PMID 24040285, 2013). "Tumor HNF1B expression is associated with venous thrombosis." (PMID 24040285, 2013). "Though this tumor type has not previously been associated with thrombosis, both tumors expressed HNF1B." (PMID 24040285, 2013).
tongue squamous cell carcinoma (1 paper, 2021). A squamous cell carcinoma that arises from the tongue. "A previous study has developed a 16-gene prognostic signature that can predict the prognosis of patients with tongue squamous cell carcinoma, including CD96, HNF1B, and SMG1." (PMID 34322156, 2021).
tumors of cervix (1 paper, 2015). "In our study, we examined HNF-1β expression in invasive carcinomas of the uterine cervix." (PMID 25884453, 2015).
ulcerative colitis (1 paper, 2024). An inflammatory bowel disease involving the mucosal surface of the large intestine and rectum. "Using the rescue experiment, which examined the effect of HD on DSS-induced ulcerative colitis after silencing HNF-1β, we demonstrated that HD indeed ameliorated UC through HNF-1β signaling." (PMID 39650157, 2024).
urinary tract obstruction (1 paper, 2021). Blockage of the normal flow of contents of the urinary tract. "Without evidence of urinary tract obstruction, we further examined HNF1B, HNF4A and WT1 immunostainings on serial embryonic sections, focusing on glomeruli with different degrees of Bowman's capsule expansion." (PMID 33737325, 2021).
uterine carcinoma (1 paper, 2018). A carcinoma involving a uterus. "Fisher’s exact tests showed significantly lower HNF-1B expression rate in the colorectal, hepatocellular, esophageal, lung, breast, bladder, prostate, and uterine carcinomas (P < .001)." (PMID 30065837, 2018).
uterine carcinosarcoma (1 paper, 2020). A usually aggressive malignant neoplasm arising from the uterine corpus and less often the cervix. "In Uterine Carcinosarcoma (UCS), HNF1B was associated with the neutrophil infiltration (r=0.442, p=9.11e-04)." (PMID 33173410, 2020).
uveal melanoma (1 paper, 2020). A melanoma derived from melanocytes of the uveal tract. "CD8+ T cell levels were negatively associated with overall survival in the low HNF1B expression group of kidney renal papillary cell carcinoma (KIRP, HR=3.76, P=0.00305) and uveal melanoma (UVM, HR=2.99, P=0.0479)." (PMID 33173410, 2020).
tumor (90 papers, 1995 to 2026). "In clear cell renal cell carcinoma, down-regulation of HNF1B was mainly observed, and its loss was associated with high-grade tumor and metastatic disease, suggesting both tumor-suppressive functions and prognostic potential, as also shown in Wilms tumor." (PMID 36672242, 2023). "Here we show that risk genotypes of the 17q12 PCa risk SNPs are associated with an elevated expression of HNF1B, thereby contributing to PCa cell proliferation and tumor progression." (PMID 36443337, 2022). "The expression of HNF1B was associated with tumour size and grade highlighting the potential of the gene as a biomarker in PDAC." (PMID 33580750, 2021). "The current review summarises the emerging role of HNF1B and its association with cancer risk in several tumours, and its importance in tumorigenesis." (PMID 33580750, 2021). "Given the unbalanced number of cases in the individual tumour subsets and their limited size, the association between HNF1B expression and clinicopathological characteristics was only analysed for the largest subset of ccRCC." (PMID 33051485, 2020). "The results of this study reveal the crucial role of HNF1B in cancer and an underlying mechanism between HNF1B and tumor-immune interactions." (PMID 33173410, 2020). "Recently, it has been shown in an animal model that the downregulation of HNF1B protein levels during tumor progression is associated with the upregulation of enoyl-CoA-(Δ) isomerase 2 (ECI2), which is one of the possible downstream targets of HNF1B31." (PMID 32873863, 2020). "None of the other evaluated parameters (gender, age, T stage of the tumour, lymphovascular invasion, presence of metastases, recurrence, or presence of HNF1B SNP variants) showed any association at a significant level." (PMID 33051485, 2020). "rs4430796 polymorphism of HNF1B gene influences independently the prognosis of EC patients with a potential effect on tumor chemo-sensitivity." (PMID 25885815, 2015). "The expression of HNF-1B in hepatocytes of non-tumor tissues was also significantly associated with DFS." (PMID 26311117, 2015). "Expression quantitative trait loci (eQTL) analysis indicates that rs4430796 is associated with altered HNF1B mRNA expression in lymphoblastoid cell lines generated from cord blood or circulating lymphocytes, and also in benign prostate tissue." (PMID 25378557, 2015). "Tumor cell lines with a mutation in HNF-1β usually show a loss of protein expression as detected by immunohistochemistry." (PMID 25884453, 2015). "Our findings support a novel mechanism of tumor-associated thrombosis in which tumor cells themselves produce clotting factors, and nominate HNF1B as marker for thrombotic risk assessment." (PMID 24040285, 2013). "The strong association between HNF1B expression and cytoplasmic clearing across diverse tumor types supports a possible causal connection." (PMID 24040285, 2013). "In particular, the connection here between HNF1B and clotting factors suggests a novel mechanism underlying tumor-associated thrombosis, with important implications for risk assessment and patient management." (PMID 24040285, 2013). "One of the possible explanations for this ambivalent character is the existence of one or more alternative splicing variants with dysregulated expression in tumour tissues which have either a regulatory role or code for HNF1B protein isoforms with different function." (PMID 34997048, 2022). "SNPs at HNF1B gene loci are also associated with biochemical failure and tumour aggressiveness." (PMID 33580750, 2021). "However, if this role were disrupted by stressors typical of tumor cells, such as aberrant metabolism (a hallmark of cancer), HNF1B would then be tumor promoting." (PMID 27732966, 2016).
tumor (continued). "Expression of HNF1β is now regarded as a hallmark of this tumor." (PMID 26375553, 2015). "HNF-1β can play an essential role in the Warburg effect of tumors by converting the glucose metabolism of tumor cells from oxidative phosphorylation to glycolysis, thereby producing more lactic acid and reducing citric acid." (PMID 38347608, 2024). "Cancer cells, on the other hand, showed high expression of HNF1B, contributing to maintaining stemness in cancer cells, a characteristic essential for tumour growth." (PMID 39149248, 2024). "Napsin A was absent in the patient tumor as well as in the tumor-derived models, by contrast to HNF1β which was heterogeneously expressed in the initial tumor." (PMID 37803448, 2023). "The tumor displayed histological features of OCCC with a heterogeneity of HNF1β expression, resulting in a diagnosis of OCCC." (PMID 37803448, 2023). "Tumour samples from CRC and ccRCC showed sporadic methylation of the HNF1B promoter, as well as the presence of truncating mutations in the HNF1B gene." (PMID 34997048, 2022). "Other studies suggested that HNF1B acts mainly as a tumour suppressor in colorectal, prostate, ovarian, and some other types of solid tumours." (PMID 34997048, 2022). "We next investigated the clinical relevance of HNF1B cell cycle signature with PCa tumor progression and severity." (PMID 36443337, 2022). "In this case, the clear tumor cells showed nuclear positivity of HNF-1β, and post-operation, two months later, local recurrence at the resection margin of the pancreas occurred." (PMID 36140448, 2022). "HNF1B profiles in different tumours throw light on different mechanisms governing HNF1B function and expression." (PMID 33580750, 2021). "The expression of HNF1B in tumour tissue, thus, can predict relapse and mortality after transplantation." (PMID 33580750, 2021). "HNF1B induced expression of clotting factors in tumour cells, including elements involved in clotting cascade like prothrombin, fibrinogen, factor XIII, contributing to prothrombotic state in malignancy." (PMID 33580750, 2021). "The function of HNF1B as a potential tumour suppressor gene has highlighted its possible role as a therapeutic target followed by identifying the role of HNF1B as a unique marker for characterizing CCCs from other lesions in ovary and endometrium." (PMID 33580750, 2021). "In contrast, the consistent hypermethylation at CpG islands associated with genes such as HNF1β, PAX2, SOX9 and WNT9B implies that epigenetic control of nephrogenesis is dysregulated in a targeted fashion in Subgroup B tumours." (PMID 33012783, 2021). "They noticed that by reducing the expression of HNF1B in these tumor cells in vitro, apoptosis was induced and led to cell death, thereby suggesting that HNF1B is required for cell survival." (PMID 34150416, 2021). "This tumor-suppressor activity is lost when HNF1B is silenced by promoter methylation in the progression to PrCa, and it is therefore no longer associated with the eQTL." (PMID 32226005, 2020). "The immunohistochemical analysis revealed that there are significant differences in HNF1B expression between the four studied tumour types." (PMID 33051485, 2020). "While the higher HNF1B expression in OCCC corelates with a higher cancer risk, on the contrary in RCC it is the lower HNF1B levels which are associated with tumour progression and poor prognosis." (PMID 32332782, 2020). "The HNF1B promoter methylation analysis was performed on the total of 53 samples of tumour tissue and 39 samples of corresponding healthy tissue, which underwent the bisulphite DNA conversion." (PMID 33051485, 2020). "Results of in vivo xenograft tumour model of DU145 cells also revealed that up‐regulation of Cyclin D1 expression rescued the growth inhibition of tumour after HNF1B overexpression." (PMID 33174391, 2020).